SESTD1 (SEC14 and spectrin domain containing 1)
Description:
May act as the primary docking protein directing membrane turnover and assembly of the transient receptor potential channels TRPC4 and TRPC5. Binds phospholipids such as phosphatidylinositol monophosphates, phosphatidylinositol diphosphates (PIP2s) and phosphatidic acid, but not less polar lipids including phosphatidylcholine, phosphatidylserine, and phosphatidylinositol. The binding to PIP2s is calcium dependent. Might be involved in the plasma membrane localization of CTNNB1.
Synonyms: SOLO; DKFZp434O0515
Tractability: PROTAC: ubiquitination databases record sites on it; its protein half-life has been measured.
Gene: Protein-coding gene on chromosome 2 (179,101,678 to 179,264,832, reverse strand). Ensembl gene ENSG00000187231.
Subcellular location (Human Protein Atlas): Intermediate filaments
Gene Ontology:
Molecular function: 1-phosphatidylinositol binding; phosphatidic acid binding; phosphatidylcholine binding; phosphatidylinositol-3,4-bisphosphate binding; phosphatidylinositol-3,5-bisphosphate binding; phosphatidylinositol-3-phosphate binding; phosphatidylinositol-4,5-bisphosphate binding; phosphatidylinositol-4-phosphate binding; phosphatidylinositol-5-phosphate binding; phosphatidylserine binding; protein binding
Biological process: negative regulation of calcium ion transmembrane transport via high voltage-gated calcium channel
Cellular component: calcium channel complex; intermediate filament cytoskeleton
Genetic constraint (gnomAD): Loss-of-function variants: 33 observed, 78.8 expected, observed/expected ratio (o/e) 0.42, 90% interval 0.32 to 0.56. The upper end of that interval is the gene's LOEUF score, 0.56, which puts it in group 2 of 6, group 1 being the genes least tolerant of losing a copy. Missense variants: 577 observed, 728.02 expected, observed/expected ratio (o/e) 0.79, 90% interval 0.74 to 0.85. Synonymous variants: 251 observed, 256.87 expected, observed/expected ratio (o/e) 0.98, 90% interval 0.88 to 1.09.
Homologues: Orthologues: chimpanzee SESTD1 (100% identical), macaque SESTD1 (99% identical), pig SESTD1 (99% identical), rat Sestd1 (99% identical), mouse Sestd1 (98% identical), dog SESTD1 (97% identical), rabbit SESTD1 (94% identical), tropical clawed frog sestd1 (91% identical), zebrafish sestd1 (84% identical). Paralogues in human: MCF2L (21% identical), TRIO (19% identical), KALRN (19% identical), MCF2 (19% identical), MCF2L2 (18% identical), PLEKHG4B (18% identical), TIAM1 (17% identical), ARHGEF40 (16% identical), TIAM2 (16% identical), PLEKHG4 (15% identical), VAV2 (13% identical), VAV1 (12% identical), and 10 more.
Diseases named in the same sentence as SESTD1 in open-access papers:
SESTD1 is named in the same sentence as 5 diseases in open-access papers, as found by Europe PMC text mining. Sharing a sentence is not in itself a finding about the gene and the disease. The quoted sentences say what the papers report.
brain disorder (1 paper, 2015). A disease affecting the brain or part of the brain. "Future experiments will explore whether dysregulation of SESTD1 may make a causal contribution to the pathogenesis of certain brain disorders." (PMID 26272757, 2015).
cancer (1 paper, 2025). A tumor composed of atypical neoplastic, often pleomorphic cells that invade other tissues. "SESTD1 is upregulated in a variety of cancers and may serve as a potential prognostic indicator and therapeutic target." (PMID 41016345, 2025).
cardiovascular disease (1 paper, 2024).
Tumor (1 paper, 2025). "The relationship between SESTD1 expression and immune-infiltration levels was investigated in the Tumor Immune Estimation Resource (TIMER)." (PMID 41016345, 2025).
SESTD1 also shares sentences with these, for which no sentence is quoted: hepatocellular carcinoma (1 paper).